RNF6 (ring finger protein 6)
Description:
E3 ubiquitin-protein ligase mediating 'Lys-48'-linked polyubiquitination of LIMK1 and its subsequent targeting to the proteasome for degradation (By similarity). Negatively regulates axonal outgrowth through regulation of the LIMK1 turnover (By similarity). Mediates 'Lys-6' and 'Lys-27'-linked polyubiquitination of AR/androgen receptor thereby modulating its transcriptional activity. May also bind DNA and function as a transcriptional regulator (By similarity). Mediates polyubiquitination of QKI in macrophages, leading to its degradation (By similarity).
Synonyms: DKFZp686P0776
Tractability: PROTAC: ubiquitination databases record sites on it.
Gene: Protein-coding gene on chromosome 13 (26,132,115 to 26,222,460, reverse strand). Ensembl gene ENSG00000127870.
Subcellular location: Nucleus; Cytoplasm; Cell projection, axon; Nucleus, PML body
Subcellular location (Human Protein Atlas): Nuclear membrane
Pathways (Reactome):
Immune System: Antigen processing: Ubiquitination & Proteasome degradation
Gene Ontology:
Molecular function: nuclear androgen receptor binding; protein binding; ubiquitin protein ligase activity; ubiquitin-protein transferase activity; DNA binding
Biological process: positive regulation of DNA-templated transcription; protein K27-linked ubiquitination; protein K6-linked ubiquitination; regulation of androgen receptor signaling pathway; regulation of DNA-templated transcription; negative regulation of axon extension; protein K48-linked ubiquitination; protein ubiquitination; ubiquitin-dependent protein catabolic process
Cellular component: cytoplasm; nuclear membrane; nucleus; axon; PML body
Genetic constraint (gnomAD): Loss-of-function variants: 25 observed, 57.93 expected, observed/expected ratio (o/e) 0.43, 90% interval 0.31 to 0.6. The upper end of that interval is the gene's LOEUF score, 0.6, which puts it in group 2 of 6, group 1 being the genes least tolerant of losing a copy. Missense variants: 697 observed, 875.27 expected, observed/expected ratio (o/e) 0.8, 90% interval 0.75 to 0.85. Synonymous variants: 252 observed, 307.44 expected, observed/expected ratio (o/e) 0.82, 90% interval 0.74 to 0.91.
Homologues: Orthologues: chimpanzee RNF6 (99% identical), macaque RNF6 (96% identical), rabbit RNF6 (89% identical), dog RNF6 (89% identical), guinea pig RNF6 (73% identical), mouse Rnf6 (73% identical), rat Rnf6 (72% identical), pig RNF6 (68% identical), zebrafish rnf6 (47% identical). Paralogues in human: RLIM (39% identical), RNF38 (14% identical), RNF44 (13% identical).
Diseases named in the same sentence as RNF6 in open-access papers:
RNF6 is named in the same sentence as 39 diseases in open-access papers, as found by Europe PMC text mining. Sharing a sentence is not in itself a finding about the gene and the disease. The quoted sentences say what the papers report.
prostate carcinoma (9 papers, 2016 to 2023). A carcinoma that arises from epithelial cells of the prostate gland. "Our findings suggest a novel role of RNF6 in cell cycle regulation and provide new insights into mechanisms underlying prostate cancer progression." (PMID 35456636, 2022). "Mutations in the RNF6 gene and specific inhibition change AR transcriptional activity in xenograft models and delay the progression of prostate cancer." (PMID 34081837, 2021). "RNF6, due to its influence on numerous signaling pathways, is associated with various types of cancer, including prostate cancer, gastric cancer, colorectal cancer, breast cancer, and leukemia." (PMID 35822825, 2020). "For example, RNF6 mediates K27-linked polyubiquitination of the androgen receptor (AR), thereby recruiting the chaperone proteins to increase the oncogenic transcriptional activity of AR in prostate cancer." (PMID 35926709, 2022). "Previous studies showed that RNF6 has been found to be associated with chemoresistance of prostate cancer, therefore we wondered whether RNF6 also contributed to drug insensitivity of breast cancer." (PMID 28223545, 2017). "Therefore, RNF6 is closely associated with the growth of prostate cancer cells." (PMID 36845743, 2023). "RNF6 regulates the transcriptional activity and specificity of AR, thereby promoting the growth of prostate cancer cells." (PMID 36845743, 2023). "Here we investigated the role of the E3 ubiquitin ligase RNF6 (Ring Finger Protein 6) in cell cycle progression in prostate cancer cells." (PMID 35456636, 2022). "In this study, we observed a dramatic decrease in cell proliferation following knockdown of RNF6 in prostate cancer cells." (PMID 35456636, 2022). "A study on human prostate cancer tissue revealed increased expression of the RNF6 in hormone-refractory prostate cancer cells." (PMID 35822825, 2020). "RNF6 plays a critical role in prostate cancer progression by regulating AR transcriptional activity as a transcription factor because knockdown of RNF6 abolishes dihydrotestosterone-induced and androgen-independent AR activation." (PMID 28223545, 2017). "Previous studies have demonstrated that RNF6 as a ubiquitin ligase stabilized AR protein in prostate cancer patients, therefore, we evaluated the effects of RNF6 on the protein expression of ERα." (PMID 28223545, 2017). "Ring finger protein 6 (RNF6) is a key oncogene in both prostate cancer and leukemia, but its role is elusive in breast cancer." (PMID 28223545, 2017). "RNF6 is involved in prostate cancer progression by mediating the K63-chain ubiquitination on androgen receptor thus modulating AR transcriptional activity and specificity." (PMID 28223545, 2017). "RNF6 has been reported to be a ubiquitin ligase that mediates atypical ubiquitination of adrogen receptor and contributes to prostate cancer progression." (PMID 28223545, 2017). "RNF6 also promotes prostate cancer cell growth; however, its mechanism in ESCC is unclear." (PMID 36845743, 2023). "RNF6 was reported to promote colorectal cancer by ubiquitination of TLE1 in prostate cancer." (PMID 35568845, 2022). "RNF6 was upregulated in colorectal cancer, breast cancer, leukemia, and prostate cancer." (PMID 35568845, 2022). "RNF6 atypically polyubiquitinates at Lys‐6 and Lys‐277 and facilitates transcriptional activity of the androgen receptor (AR) because of its overexpression in prostate cancer." (PMID 34081837, 2021). "By regulating AR functions, RNF6 promotes prostate cancer growth." (PMID 34081837, 2021). "Therefore, RNF6 is proposed as an oncogene in the development and progression of prostate cancers and it is required for prostate cancer growth." (PMID 28223545, 2017). "However, RNF6 was found to mediate an atypical ubiquitination of the androgen receptor (AR) and promotes the transcriptional activity and specificity of AR in prostate cancer." (PMID 28223545, 2017).
prostate carcinoma (continued). "Therefore, RNF6 probably regulate the ERα/Bcl-xL axle for the pathophysiology of breast cancer in a manner different from its role in prostate cancer and leukemia." (PMID 28223545, 2017). "RNF6 has been found as an oncogene that is highly expressed in prostate cancer and leukemia." (PMID 28223545, 2017). "Therefore it is possible that RNF6 and USP22 contribute to prostate cancer progression by changing AR activity and stability." (PMID 27057639, 2016). "RNF6 did not change AR stability but rather its activity and it is required for prostate cancer cell growth." (PMID 27057639, 2016).
colorectal cancer (7 papers, 2020 to 2023). A primary or metastatic malignant neoplasm that affects the colon or rectum. "Zhu and Wang showed that increased RNF6 expression is associated with shorter recurrence-free survival and shorter overall survival in colorectal cancer." (PMID 35822825, 2020). "In colorectal cancer, RNF6 ubiquitinates and degrades the transcriptional TLE3 through Wnt/β-catenin pathway." (PMID 35369571, 2022). "In colorectal cancer, high RNF6 expression promotes tumor cell proliferation and metastasis, and the effect is related to RNF6-mediated TLE3 ubiquitination and degradation, followed by increased Wnt pathway activation." (PMID 36438567, 2022). "In colorectal cancer, RNF6 upregulation promotes tumorigenesis by Wnt/β-catenin or JAK/STAT3 pathways and is associated with poor outcome." (PMID 35369571, 2022). "Analogously, RNF6 expression was increased in colorectal cancer cell lines, and its knockdown led to growth inhibition." (PMID 35822825, 2020). "MicroRNA-203a molecule (miR-203a) is downregulated in colorectal cancer cells, whereas its increased expression is conducive to the silencing of RNF6, cell arrest in the G1 phase of the cell cycle, and inhibition of tumor proliferation." (PMID 35822825, 2020). "In this study, we established colon-specific RNF6 transgenic (tg) mice, and demonstrated that RNF6 overexpression accelerated colorectal carcinogenesis compared to wild-type littermates in a chemically induced colorectal cancer (CRC) model." (PMID 34611311, 2021). "Another way that RNF6 interferes with colorectal cancer cells is the Wnt/β-catenin pathway." (PMID 35822825, 2020). "Similarly, RNF183 also contributes to the carcinogenesis of colorectal cancer, similar to RNF6." (PMID 35568845, 2022). "RNF6 amplification could activate the JAK/STAT3 or Wnt/β-catenin pathway and serve as an unfavorable prognostic marker in colorectal cancer." (PMID 35568845, 2022). "In addition, RNF6 is a RING-type E3 ubiquitin-protein ligase, and its genetic amplification and overexpression are prevalent in colorectal cancer (CRC)." (PMID 36438567, 2022). "It is also interesting that there is a negative correlation between RNF6 expression and E-cadherin gene expression in colorectal cancer cells, which is related to tumor metastasis." (PMID 35822825, 2020).
breast carcinoma (6 papers, 2017 to 2022). "Further studies showed that RNF6 was closely associated with increased expression of estrogen receptor, a critical factor in the development of breast cancers." (PMID 28223545, 2017). "In the present study, we found that RNF6 was overexpressed in more than 70% of breast cancer tissues and it was associated with overall survival." (PMID 28223545, 2017). "In doxorubicin-resistant breast cancer cells, RNF6 was found to be elevated in association with increased ERα and anti-apoptotic Bcl-xL, but not pro-apoptotic Bim-1." (PMID 28223545, 2017). "To this end, we next evaluated the association of RNF6 expression and the survival period of breast cancer patients." (PMID 28223545, 2017). "The result indicated that RNF6 was associated with the survival period of breast cancer patients." (PMID 28223545, 2017). "RNF6 was highly expressed in both breast cancer tissues and it was associated with poor prognosis, then we wondered whether RNF6 contributed to breast cancer cell proliferation." (PMID 28223545, 2017). "The present study showed that RNF6 is dysregulated in more than 70% of breast cancer tissues and it is negatively associated with the survival period of breast cancer patients, which suggesting RNF6 is probably associated with its specific pathophysiological activity." (PMID 28223545, 2017). "Importantly, the relevance of ubiquitin-mediated degradation of the kinases of the pathway is supported by a recent study showing that the E3 ubiquitin ligase RNF6 interacts with MST1 promoting the degradation of this kinase in breast cancer which is associated with short survival." (PMID 36038253, 2022). "miR-26a-5p was also confirmed to inhibit breast cancer cell growth by suppression of RNF6 expression; miR-26b-5p played a suppressive role in inhibiting proliferation of breast cancer cells by negatively regulating CDK8." (PMID 35812757, 2022). "RNF6 increases the stability of estrogen receptor alpha (ERα), a key player in the pathophysiology of breast cancers." (PMID 28223545, 2017). "The present study found that RNF6 is overexpressed in more 70% of breast cancer tissues in comparison with individual para-cancerous tissues." (PMID 28223545, 2017). "RNF6 was found to be upregulated in more than 70% (20/27) of representative primary breast cancer tissues compared with their para-cancerous control tissues." (PMID 28223545, 2017). "RNF6 increased breast cancer cell proliferation, migration and reduced cell sensitivity to doxorubicin." (PMID 28223545, 2017). "Taken together, the present study demonstrates that RNF6 triggers the ERα/Bcl-xL axle thus promoting proliferation, migration and chemoresistance of breast cancer cells." (PMID 28223545, 2017). "> 95% of breast cancer patients with a low expression of RNF6 survived more than 60 months, while <80% patients expressing a high level of RNF6 survived over 60 months." (PMID 28223545, 2017). "The expression of the RNF6 was high in both primary breast cancer cells and cell lines." (PMID 35822825, 2020). "Increased cell migration is critical for the malignancy of breast cancer, therefore, we next evaluated whether RNF6 contributed to such a feature in breast cancer cells." (PMID 28223545, 2017). "However, our present study demonstrated that RNF6 is oncogenic not only because of its high expression frequency in breast cancer tissues and cells, but because of its ability to increase breast cancer cell proliferation, migration and chemoresistance." (PMID 28223545, 2017). "This analysis suggested that RNF6 probably predicted a poor prognosis of breast cancer patients." (PMID 28223545, 2017). "Therefore, this study demonstrated that there exists an RNF6/ERα/Bcl-xL axle in breast cancer which promotes cancer cell proliferation and survival." (PMID 28223545, 2017). "RNF6 was highly expressed in human breast cancer compared with their para-cancerous tissues." (PMID 28223545, 2017).
breast carcinoma (continued). "RNF6 was highly expressed in both breast cancer tissues and cell lines, we wondered whether RNF6 was clinically important." (PMID 28223545, 2017). "Using scratch wound healing assay, a widely accepted method to measure cell migration, we found that MCF-7 cells with transfected RNF6 displayed stronger healing ability than control cells, suggesting that RNF6 might contribute to breast cancer cell migration." (PMID 28223545, 2017). "The results showed that both ADR and 5AHQ could downregulate RNF6 expression in breast cancer cells in a concentration- and time-dependent manner." (PMID 28223545, 2017). "All the results clearly showed that RNF6 was dysregulated in breast cancer tissues." (PMID 28223545, 2017). "RNF6 was markedly downregulated by shRNF6 which attenuated breast cancer cell proliferation." (PMID 28223545, 2017). "Targeting the RNF6/ERα/Bcl-xL axle could be a promising strategy in the treatment of breast cancer." (PMID 28223545, 2017). "Targeting the RNF6/ERα axle could be a promising strategy for the treatment of breast cancers." (PMID 28223545, 2017). "Therefore, it could be concluded that RNF6 probably modulates the ERα/Bcl-xL axle in breast cancer cells." (PMID 28223545, 2017). "Therefore, RNF6 has been demonstrated as an oncogene, but its specific roles in breast cancers are not yet understood." (PMID 28223545, 2017).
leukemia (6 papers, 2016 to 2023). A malignant (clonal) hematologic disorder, involving hematopoietic stem cells and characterized by the presence of primitive or atypical myeloid or lymphoid cells in the bone marrow and the blood. "Furthermore, we demonstrate the anti-leukemic drug Nilotinib and anti-myeloma drug Panobinostat (LBH589) induce RNF6 K48-linked polyubiquitination and degradation in both multiple myeloma (MM) and leukemia cells." (PMID 35926709, 2022). "This study provides an in-depth understanding on the modulation of RNF6 auto-ubiquitination and initiated the concept that chemical induction of auto-ubiquitination represents a novel strategy for the treatment of leukemia and myeloma." (PMID 35926709, 2022). "Recently we found that RNF6 is overexpressed in hematological cancers, including leukemia, lymphomas and multiple myeloma as a direct gene of the transcription factor Pbx1." (PMID 28223545, 2017). "Recently, we found that RNF6 is highly expressed in leukemia, myeloma, and other hematological malignancies and contributes to leukemia cell proliferation in vitro and in vivo." (PMID 28223545, 2017). "RNF6 induces the proliferation of leukemia cells, whereas knockdown of RNF6 delayed the growth of tumors derived from human leukemia cell line K562 in mice." (PMID 28223545, 2017). "The physiological functions of RNF6 are poorly understood, but recently one report showed that RNF6 was overexpressed in various leukemia cells, and induced proliferation of these cells." (PMID 27249653, 2016). "We found that PBX1 acts as a transcription factor to upregulate RNF6 in leukemia cells." (PMID 37324936, 2023). "The significance of the present study is that triggering RNF6 auto-ubiquitination by certain chemical compounds could be a potential novel method to induce MM and leukemia cell death." (PMID 35926709, 2022). "Knockdown of RNF6 leads to shrinkage of human leukemia xenografts in mice." (PMID 35926709, 2022). "Consistently, reexpression of RNF6 ablates drug-induced MM and leukemia cell apoptosis." (PMID 35926709, 2022). "Moreover, downregulation of RNF6 by the natural product saponins from Paris forrestii induces leukemia cell apoptosis." (PMID 35926709, 2022). "We propose that chemical induction of RNF6 auto-ubiquitination and degradation could be a novel strategy for the treatment of hematological malignancies including MM and leukemia." (PMID 35926709, 2022). "Moreover, we found that induction of RNF6 auto-ubiquitination and proteasomal degradation leads to myeloma and leukemia cell death." (PMID 35926709, 2022). "The effects of USP7 on RNF6 protein were further recapitulated in MM and leukemia cell lines." (PMID 35926709, 2022). "All these studies suggest RNF6 could be a potential therapeutic target for both MM and leukemia." (PMID 35926709, 2022). "Given that the downregulation of RNF6 protein could trigger MM and leukemia cell apoptosis and auto-ubiquitination could lead to RNF6 degradation, we wondered whether induction of RNF6 auto-ubiquitination and degradation could lead to MM and leukemia cell death." (PMID 35926709, 2022). "In the present study, we provided comprehensive evidence that the RING family ubiquitin ligase RNF6 undergoes auto-ubiquitination, and induction of RNF6 auto-ubiquitination could be a promising strategy for the treatment of some hematological malignancies such as MM and leukemia." (PMID 35926709, 2022). "In leukemia cells, RNF6 is upregulated by the Pre-B-Cell Leukemia Transcription Factor 1 (PBX1) and promotes leukemia progression." (PMID 35926709, 2022).